QKI (QKI, KH domain containing RNA binding)
Diseases named in the same sentence as QKI in open-access papers (continued):
Sharing a sentence is not in itself a finding about the gene and the disease.
head and neck squamous cell carcinoma (2 papers, 2024 to 2025). A squamous cell carcinoma that arises from any of the following anatomic sites: lip and oral cavity, nasal cavity, paranasal sinuses, pharynx, larynx, and salivary glands. "It has been found that hypoxia can downregulate QKI expression by inducing miR-5100 in head and neck squamous cell carcinoma." (PMID 40263288, 2025). "Recently, it has also been found that the exosome miR‐5100 in hypoxic head and neck squamous cell carcinoma (HNSCC) promotes CAF activation by coordinating the QKI/AKT/STAT3 axis, which further facilitates the metastasis of HNSCC." (PMID 39015555, 2024).
hepatocellular carcinoma (2 papers, 2022 to 2025). A malignant tumor that arises from hepatocytes. "In hepatocellular carcinoma (HCC), knockdown of QKI significantly reduced circular RNA zinc-finger protein with KRAB and SCAN domains 1 (circZKSCAN1) expression in HCC cell lines SMMC7721 and HCC-LM342." (PMID 35879346, 2022).
leukemia (2 papers, 2015 to 2018). A malignant (clonal) hematologic disorder, involving hematopoietic stem cells and characterized by the presence of primitive or atypical myeloid or lymphoid cells in the bone marrow and the blood. "QKI being a target of miR-155 at least in certain conditions, we would expect its expression to be reduced in leukemias presented with high miR-155 levels, such as CLL or AML." (PMID 26337206, 2015). "Finally, B-CLL patients show lower levels of QKI expression compared with B cells from healthy donor, and Qki is similarily downregulated with the progression of leukemia in Eμ-miR-155 transgenic mice." (PMID 26337206, 2015).
metastatic tumor (2 papers, 2022 to 2025). "The results indicated that, compared to primary tumor tissues, the expression levels of PTBP3, RBFOX1, SRRM2, YBX3, and QKI were significantly higher in metastatic tumor tissues." (PMID 40270362, 2025).
osteoporosis (2 papers, 2020 to 2025). A condition of reduced bone mass, with decreased cortical thickness and a decrease in the number and size of the trabeculae of cancellous bone (but normal chemical composition), resulting in increased fracture incidence. "Then, to investigate the effects of QKI deficiency on the bone mass change under pathological conditions, such as osteoporosis after losing estrogen protection, an ovariectomy (OVX) mouse model was established." (PMID 32382069, 2020). "For instance, QKI might be suggested as a biomarker for glucocorticoid-induced osteoporosis, LINC01119 might be identified as a marker associated with osteoporosis risk, and PITX1 might be linked to senile osteoporosis." (PMID 41282593, 2025). "Taken together, our data suggest that QKI deficiency promoted OC differentiation and disrupted bone metabolic balance, and eventually led to osteopenia under physiological conditions and aggravated the degree of osteoporosis under pathological conditions." (PMID 32382069, 2020). "In addition, we also found that a QKI deficiency would exacerbate pathological osteopenia, suggesting that a QKI deficiency could be considered a possible risk factor for osteoporosis." (PMID 32382069, 2020).
ovarian carcinoma (2 papers, 2020 to 2025). A malignant neoplasm originating from the surface ovarian epithelium. "The overlapping action of QKI and RBFOX2 in splicing regulation has also been reported in ovarian cancer, and global splicing analysis of eight solid cancer varieties has revealed a high overlap of exons that contained both QKI and RBFOX2 motifs in the flanking introns." (PMID 40207498, 2025). "For example, QKI showed enriched eCLIP at RBFOX2 knockdown-excluded exons, and there was significant correlation in splicing changes upon knockdown of RBFOX2 or QKI (R2 = 0.19, P = 1.2 × 10−5), matching previous observations in SKOV3ip1 ovarian cancer cells." (PMID 32728246, 2020).
pancreatic cancer (2 papers, 2022 to 2025). "Under the effect of ceRNA regulation, cascades ADAM12, MET, QKI, SEC23A, and ZEB2 were reported as PDAC disease signatures that significantly impacted the survival rates of pancreatic cancer patients." (PMID 40728965, 2025). "QKI has been identified as a splicing signature that can distinguish basal-like PDAC subtypes and may predict worse clinical outcomes in pancreatic cancer." (PMID 40728965, 2025).
renal cell carcinoma (2 papers, 2020 to 2025). "Moreover, QKI maybe an independent factor that influences the prognosis of renal cell carcinoma, and therefore may serve as a potential diagnostic and therapeutic target." (PMID 32047543, 2020). "In renal cell carcinoma (RCC), CircSPIRE1 was identified as a metastasis-inhibiting circular RNA that suppresses the mesenchymal state through upregulating QKI expression." (PMID 41222726, 2025).
Sepsis (2 papers, 2017 to 2022). Sepsis is defined as life-threatening organ dysfunction caused by a dysregulated host response to infection. "This study aimed to investigate the role of QKI in regulation of host–pathogen interaction in MRSA-induced sepsis and explored the underlying mechanisms." (PMID 36088389, 2022). "To further explore the therapeutic role of QKI in sepsis with pathogen infection, we constructed lipid-coated particles encapsulated with QKI specific siRNA, termed as “siQKI-LCP”." (PMID 36088389, 2022). "Encouraged by the results from septic patients, we further explored the role of QKI in monocytes/macrophages during sepsis progression using myeloid-specific QKI knockout mice (LysM+QKIfl/fl)." (PMID 36088389, 2022). "In summary, we demonstrated QKI ablation in macrophages was protective in MRSA induced sepsis model." (PMID 36088389, 2022). "Our data demonstrated for the first time that QKI could serve as a novel prognostic marker and therapeutic target in sepsis." (PMID 36088389, 2022). "Furthermore, QKI mRNA levels in peripheral blood monocytes from sepsis patients were decreased with the increasing level of serum procalcitonin (an indicator of the severity of the infection)." (PMID 36088389, 2022). "Moreover, we noticed a significantly reduced level of QKI in monocytes and PBMCs of whole blood collected from septic patients and QKI mRNA level decreased as sepsis progressed." (PMID 36088389, 2022). "Therefore, modulating the QKI expression level may be a potential way to treat macrophage-mediated inflammatory diseases such as sepsis." (PMID 29276519, 2017). "In accord with the mRNA results, the level of QKI protein was decreased in both PBMC and monocytes in sepsis patient." (PMID 36088389, 2022).
thyroid cancer (2 papers, 2020 to 2022). "MiR−574-5p by targeting QKI proteins could promote G1/S transition and apoptosis in thyroid cancer cells via Wnt/β-catenin signaling pathway." (PMID 33330110, 2020).
triple-negative breast carcinoma (2 papers, 2022 to 2024). An invasive breast carcinoma which is negative for expression of estrogen receptor (ER), progesterone receptor (PR), and human epidermal growth factor receptor 2 (HER2). "It has been recently reported that circDDX21 functions as a sponge for miR-1264 to regulate QKI expression in triple-negative breast cancer." (PMID 38773094, 2024).
adenoma (1 paper, 2022). A neoplasm arising from the epithelium. "Furthermore, we detected the methylation level of the QKI promoter in eight adenoma tissues and nine hyperplastic polyp tissues." (PMID 36017498, 2022). "A long non-coding RNA (lncRNA) named CAHM (chr6: 163,834,097–163,834,982), located adjacent to the QKI gene, has been demonstrated to be specifically hypermethylated in CRC and adenoma, with a low methylation level in the tissue of lung, prostate, and breast cancers." (PMID 36017498, 2022).
anaplastic astrocytoma (1 paper, 2015). "QKI expression is also a characteristic of glial progenitors, and a high frequency of deletion of chromosome 6q26-27, containing QKI, was observed in anaplastic astrocytoma and GBM." (PMID 25971746, 2015).
Autoimmunity (1 paper, 2022). The occurrence of an immune reaction against the organism's own cells or tissues. "Another regulator QKI alters inflammation by downstream regulation of the AHR and NFκB signalling and as such, similar to the Fox genes can also regulate autoimmunity." (PMID 35328504, 2022).
bladder tumor (1 paper, 2020). "Furthermore, downregulation of miR-362-5p inhibited bladder tumor growth and increased QKI expression." (PMID 32194406, 2020).
cataract (1 paper, 2024). Partial or complete opacity of the crystalline lens of one or both eyes that decreases visual acuity and eventually results in blindness. "Follow-up analysis of the shared loci implicates candidate genes QKI, STK17A, TYR, NSF, and TCF4 likely contribute to the pathophysiology of cataracts and hearing difficulties." (PMID 38632618, 2024).
chronic lymphocytic leukemia (1 paper, 2015). "Similarly, the p38 pathway is also a target of QKI activity in chronic lymphocytic leukemia (CLL)-derived MEC2 cells." (PMID 26337206, 2015).
chronic obstructive pulmonary disease (1 paper, 2022). A chronic and progressive lung disorder characterized by the loss of elasticity of the bronchial tree and the air sacs, destruction of the air sacs wall, thickening of the bronchial wall, and mucous accumulation in the bronchial tree. "Moreover, QKI was identified as a significantly altered gene in the ciliated epithelial cells of lungs affected by chronic obstructive pulmonary disease (COPD), a disease that is primarily caused by tobacco smoking." (PMID 37521848, 2022).
colitis (1 paper, 2021). Inflammation of the colon. "QKI-deficient mice with DSS induced the disproportional changes of microbiota which mediated severe DSS colitis in FMT mice." (PMID 33758177, 2021). "All the results of sequencing analysis indicate that myeloid QKI-deficiency alters the proportion of microbiota in mice colitis, which shall contribute to the development of severe colitis phenotypes." (PMID 33758177, 2021). "Next, we evaluated the susceptibility of QKI-deficient mice to DSS-induced colitis (WT-DSS; KO-DSS)." (PMID 33758177, 2021). "Moreover, the expression of QKI in CD11b+F4/80+ monocytes was significantly increased in the DSS-induced colitis mouse models, which was detected by flow cytometry." (PMID 33758177, 2021).
demyelinating disease (1 paper, 2025). A broad group of disorders that affect the myelin sheaths that cover the neurons. "Given its central role in glial cell function, we focused on QKI, an RNA-binding protein crucial for neuroinflammation, as its dysregulation has been linked to demyelinating diseases." (PMID 40759954, 2025).
developmental delay (1 paper, 2023). "QKI probably has an additive effect on the level of developmental delay next to the deletion of DLL1, which on its own can lead to moderate developmental delay in small (500 kb) deletions." (PMID 36935482, 2023). "Normal development was seen in a couple of individuals without a deletion of QKI, whereas severe developmental delay was only seen in individuals with a deletion including QKI." (PMID 36935482, 2023).
diffuse large B-cell lymphoma (1 paper, 2024). "Additionally, QKI is associated with the prognosis of diffuse large B-cell lymphoma (DLBCL), NSCLC, and leukemia." (PMID 39479357, 2024).
emphysema (1 paper, 2021). "QKI expression appeared to decrease according to % emphysema (n = 208; p = 0.0854), whereas, IGFBP5 expression significantly increased according to % emphysema (p = 0.0150)." (PMID 33823868, 2021). "Further, we determined whether QKI and IGFBP5 gene expressions in whole lung tissue correlated with emphysema severity." (PMID 33823868, 2021).
endometrial cancer (1 paper, 2022). Primary or metastatic malignant neoplasm involving the endometrium (mucous membrane that lines the endometrial cavity). "In addition, we can see that the endometrial cancer pathway directly related to tumor development contains three genes of QKI, CTNNA1, GSK-3b." (PMID 35068348, 2022).
Hepatic steatosis (1 paper, 2024). Steatosis is a term used to denote lipid accumulation within hepatocytes. "Providing that QKI has been previously associated with cholesterol biosynthesis, lipid metabolism, liver triglycerides, and hepatic steatosis, we aimed to evaluate the influence of plant miR8126-3p on target genes and lipid metabolism in human hepatocyte HepG2 cell model." (PMID 38338999, 2024). "Intriguingly, both miR8126 isoforms downregulated QKI and MAPKAPK2 gene expression in the HepG2 model that mimicked hepatic steatosis, despite prediction algorithms reporting that miR8126-3p could target QKI and miR8126-5p could target MAPKAPK2, and not vice versa." (PMID 38338999, 2024).
hypertrophic cardiomyopathy (1 paper, 2023). A condition in which the myocardium is hypertrophied without an obvious cause. "One (1/42) of our patients (Id185, aged 1.5 years) with a deletion including QKI was reported to have hypertrophic cardiomyopathy." (PMID 36935482, 2023).
injury (1 paper, 2012). Damage inflicted on the body as the direct or indirect result of an external force, with or without disruption of structural continuity. "Following nerve injury QKI is post-translationally modified as observed by the shift in the protein band, while p75NTR is up-regulated as indicated by the unmodified nascent protein (∼50 KDa, lower band in P75NTR blot)." (PMID 22792185, 2012).
ischemia (1 paper, 2020). A hypoperfusion of the BLOOD through an organ or tissue caused by a PATHOLOGIC CONSTRICTION or obstruction of its BLOOD VESSELS, or an absence of BLOOD CIRCULATION. "Both miR-208a-3p and miR-208b-3p reduce the expression of the RNA-binding protein Quaking, encoded by gene QKI, which inhibits the apoptosis of cardiomyocytes under ischemia/reperfusion condition." (PMID 32194626, 2020).
metastasis (1 paper, 2020). The spread or migration of cancer cells from one part of the body (where they first appeared) to another. "The downregulation of QKI due to promoter hypermethylation was detected in GC tissues and correlated with a poorer differentiation status, greater invasion depth, gastric lymph node metastasis, distant metastasis, advanced TNM stage and poorer patient survival." (PMID 32931453, 2020).
rectum adenocarcinoma (1 paper, 2022). An adenocarcinoma arising from the rectum. "In contrast, for only rectum adenocarcinoma, QKI and RBM8A were recognized as such." (PMID 35885025, 2022).
renal carcinoma (1 paper, 2020). A carcinoma arising from the epithelium of the renal parenchyma or the renal pelvis. "We noted that HIF-1α, which is highly expressed in VHL-mutated renal cancer cells, acts as a downstream effector of QKI." (PMID 32047543, 2020). "QKI overexpression or knockdown was assessed in renal cancer cells." (PMID 32047543, 2020).
renal fibrosis (1 paper, 2020). A final common manifestation of a wide variety of chronic kidney diseases characterized by glomerulosclerosis and tubulointerstitial fibrosis. "Thus, diminishing expression or reducing QKI activity in monocytes and macrophages could serve as an effective means of limiting renal fibrosis in the damaged kidney." (PMID 34968236, 2020).
Stroke (1 paper, 2025). Sudden impairment of blood flow to a part of the brain due to occlusion or rupture of an artery to the brain. "Reasoning that these features may affect translation in part through selection by specific RNA-binding proteins, we tested the association between differential expression in stroke and dependence on the Quaking RNA-binding protein (QKI)." (PMID 39796165, 2025).
Wilms tumor (1 paper, 2022). An embryonal neoplasm characterized by the presence of epithelial, mesenchymal, and blastema components. "This might also explain the heterogeneity in expression levels of QKI, and also the fact that unlike ESRP1 and ESRP2, the expression levels of RBFOX2 in the Wilms’ tumor xenograft samples are heterogeneous and not similar to those in hFK1." (PMID 36380228, 2022).
tumor (77 papers, 2013 to 2025). "Aberrant expression or mutation of QKI in ECs can result in pro- or anti-angiogenic effects under different physiological and pathological conditions, including tumor angiogenesis." (PMID 41222726, 2025). "QKI plays a regulatory role in multiple aspects of tumor progression, including tumor growth, metastasis, and angiogenesis, and is associated with prognosis." (PMID 39479357, 2024). "This study also demonstrated that MYB-QKI fusion was able to drive tumorigenesis via simultaneous activation of MYB as a result of enhancer translocation combined with the loss of the tumor suppressor activity of QKI." (PMID 36699536, 2022). "As QKI has previously been implicated to have tumour suppressive roles, we tested its ability to regulate colony formation, a measure of anchorage independent cell growth." (PMID 29871889, 2018). "QKI is a tumor suppressor gene that encodes for a RNA-binding protein; QUAKING, that plays a role in the development of the CNS, among other organs." (PMID 29654229, 2018). "Quaking (QKI) is a tumor-suppressor gene encoding a conserved RNA-binding protein, whose expression is downregulated in several solid tumors." (PMID 26337206, 2015). "This provides a novel mechanism underlying QKI’s tumor-suppressive effects in cancer cells." (PMID 40052530, 2025). "In most instances, QKI serves as a target gene for miRNAs, including miR-155, miR-221, miR-200c, miR-200, miR-574-5p, miR-143-3p, and miR-362-5p, which mostly are associated with tumor proliferation and migration." (PMID 39479357, 2024). "QKI regulated the splicing of actin cytoskeleton-associated genes and promoted a pro-mesenchymal phenotype, cell migration, and invasion while restraining tumor growth in vivo." (PMID 38325381, 2024). "QKI gene encodes an RNA-binding protein that regulates the functions of diverse mRNAs, which play critical parts in tumorigenesis through inactivation of tumor suppressor genes in multiple tumors." (PMID 33692952, 2021). "In support of this hypothesis, QKI has been considered a tumor suppressor in various cancers and frequently associated with MacroH2A1.1 downregulation." (PMID 31164793, 2019). "Low QKI expression is a risk factor for tumor recurrence after surgery." (PMID 31440515, 2019). "Thus, QKI has the function of reducing the stemness of tumor cells, and the loss of QKI may affect downstream RNA targets involved in carcinogenesis, transformation, or angiogenesis, potentially being an important condition for the progression of GBMs." (PMID 39479357, 2024). "RNA sequencing identified the oncogenic fusion MYB/MYBL1::QKI, a known driver of this tumour subtype." (PMID 41033792, 2025). "QKI stabilization of CCND1 in tumor ECs in turn promoted tumor EC proliferation, tumor angiogenesis and metastases." (PMID 41222726, 2025). "Several reports have demonstrated direct roles of QKI in tumor EC biology, as well as how cancer cell expression of QKI regulates tumor angiogenesis." (PMID 41222726, 2025). "Among the eight significant mutated genes, CDK12, CTNNB1, and MLH1 were tested in both tumor and blood, whereas CTCF, IGF1R, IKBKE, QKI, and TIPARP were only tested in tDNA." (PMID 40227722, 2025). "This regulation suppresses tumor cell proliferation and inhibits the activation of the Notch signaling pathway, highlighting a critical role of QKI-mediated splicing control in tumor suppression." (PMID 41196940, 2025). "QKI is also involved in epithelial–mesenchymal transition (EMT) in the tumor development of multiple epithelial-derived cancer types." (PMID 41222726, 2025). "Hypoxia/HIF1α regulated transcriptionally miR-5100 to promote the degradation of its target gene QKI, which acts as a tumor suppressor in HNSCC." (PMID 38485986, 2024). "The biological functions of the FTO/GAS5/IGF2BP2/QKI axis was assessed using the tumor xenograft assay." (PMID 38782769, 2024).